ASB16 (ankyrin repeat and SOCS box containing 16)
Description:
May be a substrate-recognition component of a SCF-like ECS (Elongin-Cullin-SOCS-box protein) E3 ubiquitin-protein ligase complex which mediates the ubiquitination and subsequent proteasomal degradation of target proteins.
Synonyms: FLJ30165
Tractability: No criterion of Open Targets' tractability assessment is met for any kind of drug.
Gene: Protein-coding gene on chromosome 17 (44,170,447 to 44,179,084, forward strand). Ensembl gene ENSG00000161664.
Subcellular location (Human Protein Atlas): Focal adhesion sites
Pathways (Reactome):
Immune System: Antigen processing: Ubiquitination & Proteasome degradation
Metabolism of proteins: Neddylation
Gene Ontology:
Molecular function: protein binding
Biological process: intracellular signal transduction; protein ubiquitination
Cellular component: cytosol
Genetic constraint (gnomAD): Loss-of-function variants: 42 observed, 32.36 expected, observed/expected ratio (o/e) 1.3, 90% interval 1.01 to 1.67. The upper end of that interval is the gene's LOEUF score, 1.67, which puts it in group 6 of 6, group 1 being the genes least tolerant of losing a copy. Missense variants: 597 observed, 501.05 expected, observed/expected ratio (o/e) 1.19, 90% interval 1.11 to 1.27. Synonymous variants: 268 observed, 230.05 expected, observed/expected ratio (o/e) 1.16, 90% interval 1.05 to 1.29.
Homologues: Orthologues: chimpanzee ASB16 (98% identical), macaque ASB16 (97% identical), pig ASB16 (89% identical), dog ASB16 (89% identical), mouse Asb16 (85% identical), rat Asb16 (85% identical), rabbit ASB16 (79% identical), guinea pig ASB16 (66% identical), tropical clawed frog asb16 (47% identical), zebrafish asb16 (47% identical). Paralogues in human: ASB18 (37% identical), ASB10 (36% identical), ASB4 (29% identical), ASB14 (25% identical), ASB15 (21% identical), ASB3 (20% identical), MPHOSPH8 (19% identical).
Diseases named in the same sentence as ASB16 in open-access papers:
ASB16 is named in the same sentence as 3 diseases in open-access papers, as found by Europe PMC text mining. Sharing a sentence is not in itself a finding about the gene and the disease. The quoted sentences say what the papers report.
bipolar disorder (1 paper, 2025). A disorder of the brain that causes unusual shifts in mood, energy, activity levels and the ability to carry out day-to-day tasks. "The minor allele at rs7212573 is associated with increased unproductive splicing of ASB16, which results in decreased expression of ASB16 and an increase in risk for bipolar disorder." (PMID 40291686, 2025).
lung adenocarcinoma (1 paper, 2020). A carcinoma that arises from the lung and is characterized by the presence of malignant glandular epithelial cells. "Our study identified several genes that may be associated with the survival of lung adenocarcinoma, in particular two new genes (ASB16, NEDD4)) that provide evidence for the prognosis of lung adenocarcinoma, and further studies are needed to confirm our findings." (PMID 34007304, 2020).
ASB16 also shares sentences with these, for which no sentence is quoted: cancer (1 paper).